LEP (leptin)
Diseases named in the same sentence as LEP in open-access papers (continued):
Sharing a sentence is not in itself a finding about the gene and the disease.
Obesity (continued). "However, in the present study, it failed to measure because most of the levels were beyond the detecting range of the kit, which raises an important point that leptin may be a more sensitive indicator than IL-1β in HFD-induced obesity-related OA rats." (PMID 34457118, 2021). "Evidence is emerging that activation of histamine signaling in the hypothalamus might have substantial anti-obesity and antidiabetic functions, and hypothalamic histamine H1 and H3 receptors are involved in the regulation of food rhythm, leptin resistance, and diabetes." (PMID 34950689, 2021). "In addition to leptin’s role in hormonal food intake regulation via the inhibition of reward signalling, previous research has also shown that before RYGB surgery most individuals with obesity have very high levels of leptin when in a fasted state, yet its ability to signal satiety is impaired." (PMID 33615220, 2021). "Interestingly, maternal pre-pregnancy obesity was not a significant predictor of LEP methylation, but it was strongly associated with GDM." (PMID 34502370, 2021). "Therefore, obesity may be supported by the rewarding properties of fast food, and lead to tolerance due to leptin and other hormonal imbalance, a phenomenon which further lead to lack of appetite suppression." (PMID 35082706, 2021). "Therefore, correcting leptin resistance is essential for the reversal of obesity." (PMID 33868169, 2021). "For these reasons, BAT is emerging as an interesting and promising target for therapeutic intervention in obesity and metabolic disease, and leptin-induced thermogenesis could be designed as a new promising strategy to counteract obesity and related metabolic derangements." (PMID 34208585, 2021). "Indeed, the genus Bacteroides was negatively correlated with the gene expression of hypothalamic PPAR-γ, which contributes to HFD-induced leptin resistance, a condition that leads to the development of obesity and metabolic disorders, such as insulin resistance and dyslipidemia." (PMID 34381356, 2021). "In obesity, dyslipidemia and changes in circulating leptin serum values may also be present." (PMID 33985516, 2021). "However, unlike that in congenital leptin deficiency, leptin concentrations are elevated in obesity owing to large fat mass, and systemic leptin signaling is blunted despite high circulating leptin levels." (PMID 33935782, 2021). "Interestingly, CB1-dependent endocannabinoid signaling in SF1 neurons interferes with the action of leptin in lean animals, while this same signaling may protect from diet-induced obesity." (PMID 34718828, 2021). "Indeed, leptin circulating levels are proportional to the body fat mass and dramatically altered in condition of both chronic negative and positive energy balance so that malnutrition leads to hypoleptinemia, while obesity to hyperleptinemia." (PMID 33804765, 2021). "Our findings indicated that leptin may be one of the initiating factors of obesity-related OA." (PMID 34457118, 2021). "Acupuncture may reduce the expression levels of prostaglandin e and leptin to regulate obesity." (PMID 34646336, 2021). "Obesity is a systemic and tissue-specific condition that can lead to chronic inflammation and oxidative stress, that produces an unregulated and persistent synthesis and secretion of chemokines and cytokines by innate immune cells, and adipokines (e.g. leptin and lipocalin) from adipocytes." (PMID 33710838, 2021). "This could suggest that these animals, despite being exposed to an adverse nutritional condition during fetal life, are more sensitive to the central action of leptin and, therefore, may be more protected against the development of obesity and its related comorbidities in adulthood." (PMID 34579137, 2021).
Obesity (continued). "Our data demonstrates an important role for basal autophagy or leptin-induced autophagy in leptin-induced migration and ERK phosphorylation in breast cancer cell lines, suggesting a potential use for the inhibition of autophagy in breast cancer associated with obesity." (PMID 33763424, 2021). "Thus, the existing dogma in the field is that while physiological leptin concentrations may exert endothelium-dependent vasodilatory effects, pathophysiological elevated leptin levels akin to obesity and diabetes exhibit multiple proatherogenic properties." (PMID 34064112, 2021). "However, in obesity, a prolonged increase in plasma leptin levels leads to decreased detection of the peripheral energy status, which culminates in ineffective satiety detection despite high energy storage and leptin levels." (PMID 34444990, 2021). "Thus, changes in leptin signaling during obesity can produce expected changes in oocyte metabolism." (PMID 33924072, 2021). "Hence, increased levels of leptin signaling inhibitor suppressor of cytokine signaling (SOCS) 3 were observed already after 4 wk DIO with potential implications for ovarian pathogenesis during early obesity." (PMID 33924072, 2021). "A potential contributor to CHIP in T2D and obesity may be the adipokine leptin." (PMID 34760952, 2021). "Furthermore, chronic low-grade inflammation within the hypothalamus might also represent a possible mechanism for central leptin resistance not only in obesity but also in polycystic ovarian syndrome, as seen in murine models." (PMID 34208585, 2021). "Notably, a recent study indicated that leptin may contribute to the dysregulated/activated adipocyte autophagy and to its dysfunction in obesity." (PMID 33849593, 2021). "Furthermore, many forms of obesity result in elevated circulating leptin." (PMID 35056501, 2021). "Humans with loss-of-function mutation in leptin or leptin receptor have been found to be protected from hypertension despite obesity, nevertheless, exogenous leptin administration does not increase blood pressure in leptin deficient states including congenital leptin deficiency and lipodystrophy." (PMID 34966295, 2021). "We found that Ala12Ala genotype was significantly more frequent in females with obesity than in those without obesity, with Ala12Ala carriers having significantly higher weight and body mass index (BMI), however the association disappeared when adjusting by leptin concentrations." (PMID 34887761, 2021). "Interestingly, Epac2A KOs exhibit early morphological (e.g., increased fat deposits) and biochemical (e.g., increased leptin and decreased adiponectin serum levels) signs of obesity, but these changes are connected with suppressed hypothalamic leptin signaling." (PMID 34359828, 2021). "However, when obesity is persistent, leptin or intra-cellular lipid accumulation leads to the immune paralysis of NK cells, which might be an explanation for the higher cancer incidence in individuals with obesity." (PMID 33717101, 2021). "In addition to its role in obesity, leptin is also known to have a role in diabetes and may be implicated in energy homeostasis and insulin resistance induced by epigenetic regulation." (PMID 34828259, 2021). "Obesity may influence diet and/or food intake through dysregulation in leptin and satiety levels." (PMID 35145486, 2021). "However, many aspects concerning leptin interactions with inflammation and immune system as well as the therapeutical approaches to overcome leptin resistance and reduced vaccine effectiveness in obesity remain a challenge for future research." (PMID 33804765, 2021). "Therefore, leptin might decrease influenza‐vaccine‐specific‐IgG production in individuals with obesity." (PMID 34269511, 2021).
Obesity (continued). "In addition, people with obesity have a decreased concentration of adiponectin, which has anti-inflammatory properties, and an increased concentration of leptin, which has pro-inflammatory properties, as well as an increase in acute phase agents such as C-reactive protein (CRP) and amyloid antigen." (PMID 34960696, 2021). "In addition, obesity disturbs endocrine hormones, such as leptin, and leads to the increase of adipose tissue-specific molecules, called adipokines, generating an altered immunity that favors the intensification of the SARS-CoV-2 infection and exacerbation of the mitochondrial damage." (PMID 34976854, 2021). "Furthermore, leptin resistance in obesity plays a critical role in the formation of tau phosphorylation, which may have a detrimental effect on the impairment of RGCs." (PMID 34501469, 2021). "In addition to its antifibrotic effects, the treatment with BAPN was able to prevent the increase in O2- production observed in the aorta of the obese animals, as well as in VSMCs treated with leptin, a hormone upregulated in obesity which is involved in the vascular fibrosis observed in obese rats." (PMID 33800427, 2021). "Leptin might play a critical role in obesity-related tumorigenesis." (PMID 33925827, 2021). "Thus, C-peptide, insulin, leptin, PAI, GIP, GLP-1, ghrelin, resistin, and visfatin are closely associated with carbohydrate and lipid metabolism and BMI in obese patients, which contributes to the formation of IR in obesity." (PMID 33959145, 2021). "In addition, diet-induced obesity was shown to increase the growth rate of esophageal tumors in OE33 tumor-bearing NOD-SCID mice, which was associated with increased levels of abdominal fat and serum leptin." (PMID 33513939, 2021). "Thus, combining leptin therapies with leptin sensitizers may help overcome such resistance and, consequently, obesity." (PMID 34084149, 2021). "Indeed, chronic inflammatory states due to metabolic (i.e., obesity) or infectious diseases may increase leptin concentrations and lead to leptin resistance further fueling inflammation." (PMID 33804765, 2021). "Understanding leptin and its influence on orthodontic tooth movement could make an important contribution to the long-term success of orthodontic treatment, especially in view of the increasing obesity rates in children and adolescents." (PMID 34202165, 2021). "Pathophysiological mechanisms remain unclear, but there are many factors involved in the association between obesity and BC, such as chronic subclinical inflammation, sex hormone deregulation, insulin/IGF-1 pathways, or the secretion of different adipokines like leptin." (PMID 34202969, 2021). "These analogs were tested in various mouse and rat models of obesity, glucose intolerance/insulin resistance and T2DM resulting from high-fat (HF) diet feeding (diet-induced obesity (DIO) models) or in rodents with nonfunctional leptin signaling due to a spontaneous mutation in the leptin receptor." (PMID 34867411, 2021). "Data from in vivo research, however, allows us to highlight that PAI-1 antagonists might be an effective intervention to prevent the development of obesity and its sequelae by restoring leptin responsiveness with improved energy dissipation and thermogenic control." (PMID 34208585, 2021). "In summary, our study describes the influence of leptin on the association between obesity and NEFA levels in children, showing that, at the prepubertal age, leptin levels seem to explain the significantly lower NEFA concentrations observed in girls with obesity." (PMID 35071145, 2021). "Subsequently, a second search topic with the following keywords was performed: (obesity AND adults AND exercise AND anaerobic threshold AND physical training) AND growth hormone OR GH OR non-esterified fatty acids OR NEFA OR insulin resistance OR lactic acid OR leptin OR body composition." (PMID 34047810, 2021).
Obesity (continued). "Plasma leptin levels reflect body adiposity, and therefore act as an ‘adipostat’, whereby low leptin levels reflect a state of low body adiposity (under-nutrition/starvation) and elevated leptin levels reflect a state of high body adiposity (over-nutrition/obesity)." (PMID 34502119, 2021). "This could be attributed to a number of factors as obesity stimulates the activation of the renin-angiotensin-aldosterone system, an increase in sympathetic activity, which further promotes insulin and leptin resistance, and an increase in procoagulatory activity and endothelial dysfunction." (PMID 33898368, 2021). "Besides, leptin may contribute to the effect of central and peripheral insulin resistance on obesity; these two pathophysiological changes often work together to promote metabolic disorders in metabolic diseases." (PMID 34122341, 2021). "Given the correlation between leptin, obesity, insulin action and reproductive functions, we hypothesized that plasma leptin and sOB-R levels, and also LEP/LEPR variants might be associated with PCOS as well as infertility and recurrent pregnancy loss (RPL) in PCOS patients." (PMID 34407095, 2021). "In addition, leptin may play an important role in the relationship between obesity and colorectal cancer." (PMID 35027962, 2021). "Growing evidence suggests that insulin and leptin play significant physiological roles in cognition, and these signaling pathways may be promising therapeutic targets to alleviate cognitive impairment accompanied by obesity and MetS." (PMID 34795562, 2021). "Specifically, B. longum may decrease the GHSR-1a internalization and has been correlated with its higher acetate content, but also with decrease body weight gain, fat depot size, glucose tolerance, and leptin levels in a preclinical mouse model of HFD-induced obesity." (PMID 34458288, 2021). "Hence leptin resistance in those with obesity may result in decreased endometrial proliferation and could contribute to delayed endometrial repair at menstruation." (PMID 33836495, 2021). "A diet‐induced obesity model, previously characterized by our group, presented increased body and trunk fat percentages, higher triglyceride, total cholesterol, and insulin and leptin levels compared with lean animals, as well as greater adipose tissue compartments normalized by body weight." (PMID 34632734, 2021). "Thus, obesity may amplify resistance to the muscle-preserving effects of leptin in ageing and contribute to the sarcopenic-obese state." (PMID 33528828, 2021). "Also saponins derived from fungal endophytes could be potential inhibitors of leptin, reverse its resistance in obesity, and potentiate host immune response against multiple diseases." (PMID 33804765, 2021). "Given that L. acidophilus and L. casei have been identified as SCFA-producing bacteria, further RCTs are needed to explore their anti-obesity effects in early infancy via elucidating the mechanisms by which such bacteria could reduce the pro-inflammatory cytokines upregulated by leptin." (PMID 34835958, 2021). "Additionally, ANGPTL3 is typically downregulated by leptin and insulin, and, therefore, resistance to leptin and insulin that generally happens in obesity may be responsible for its elevated levels." (PMID 34422408, 2021). "In addition, LEP has been found to prevent obesity by contributing to lipolysis metabolism." (PMID 34944286, 2021). "Growing scientific evidence shows obesity-related conditions such as insulin resistance, type 2 diabetes, and the metabolic syndrome as well as obesity-related systemic markers (e.g., leptin, adiponectin, SHBG, insulin and the IGF axis and C-reactive protein) are associated with breast cancer." (PMID 34066392, 2021). "Indeed lowerTSH levels and hyperthyroidism are moreprevalent amongst smokers, whereas obesity, by increasing leptin levels, mightcontribute to the development of thyroid autoimmunity andhypothyroidism." (PMID 34557302, 2021).
Obesity (continued). "Finally, we asked to what extent common DEGs previously identified in CCs collected from both leptin treated and early obesity mouse protocols (4 wk HFD) could be already expressed in GC from antral and preovulatory follicles." (PMID 33924072, 2021). "However, although both animal models rely on the disruption of the leptin signaling pathway by targeting the ligand (ob/ob) or the receptor (db/db), and both models are characterized by hyperphagia, massive obesity, and fat mass gain, they are discrepant for glucose metabolism." (PMID 34183063, 2021). "Recent findings suggest that the leptin pathway may partly explain the obesity asthma relationship." (PMID 33418879, 2021). "In tumor-free human donors with obesity, the authors found that increasing leptin concentrations in the blood were positively associated with increased frequencies of PD-1+CD8+ T cells, which aligned with their murine data showing that leptin promoted increased PD-1 expression on CD8+ T cells." (PMID 34421889, 2021). "Possibly, because leptin is correlated with overall weight, it may be associated with general obesity despite the absence of central adiposity." (PMID 34426770, 2021). "In addition, obesity–related hypertension as well as various obesity-related hormones, such as leptin, adiponectin and tumor necrosis factor α could also be common links between obesity, cardiac remodeling and increased risk of AF." (PMID 34922449, 2021). "Chronic hypersecretion of stress mediators, such as glucocorticoids, may result in insulin and leptin hypersecretion, contributing to insulin and leptin resistance, along with dysregulation of appetite and food intake by inducing alterations in the reward system, finally leading to obesity." (PMID 33800718, 2021). "We examine the pleiotropic effects of leptin action, in addition to its established role in modulation of appetite, and discuss the neural circuitry mediating leptin action, and how this is altered with obesity, both centrally (leptin resistance) and in adipose tissues (sympathetic neuropathy)." (PMID 34613819, 2021). "We further examined Leptin, an adipokine, which has been associated with obesity, but could not identify significant changes between both investigated BMI groups." (PMID 34354697, 2021). "Therefore, the identification of drugs or other natural molecules able to contrast inflammation and leptin secretion may represent a useful therapeutical approach to treat obesity-related diseases." (PMID 33946540, 2021). "It is known that leptin is involved in suppressing food intake and stimulation of thermogenesis, whereas adiponectin is considered to be a pleiotropic organ-protective protein, which is produced only by adipose tissue, and is reduced with the progress of obesity." (PMID 35221861, 2021). "This selective resistance to leptin could be a key contributor to obesity-induced hypertension." (PMID 33679451, 2021). "Moreover, leptin deficiency in humans was associated with obesity and metabolic syndrome, without SNS activation or hypertension." (PMID 34068919, 2021). "Hence, advances in our understanding of the role of leptin on ovarian pathophysiology during obesity should unravel innovative tools to monitor the quality of the oocyte during disease progression, potentially preventing pregnancy failure and ensuring the birth of a healthy offspring." (PMID 33924072, 2021). "In addition, the leptin pathway, which is characteristically overexpressed in obesity, may exhaust T cells through PD-1 immune checkpoint overexpression." (PMID 34063692, 2021). "This could have important implications since plasma leptin and resistin levels correlate with adiposity, and both can be elevated in obesity and overweight conditions." (PMID 33679451, 2021).